LATS2 (large tumor suppressor kinase 2)
Diseases named in the same sentence as LATS2 in open-access papers (continued):
Sharing a sentence is not in itself a finding about the gene and the disease.
infection (5 papers, 2011 to 2022). The state of being infected such as from the introduction of a foreign agent such as serum, vaccine, antigenic substance or organism. "The results showed that LATS2 rs9552315 was associated with infection of H. pylori in codominant and dominant models." (PMID 32423384, 2020). "In human islets, LATS2 was silenced by siRNA-mediated transfection as well as adenoviral-mediated infection either with Ad-shLATS2 or control shScr viruses." (PMID 34389720, 2021). "Altogether, these results reveal an unexpected mechanism involved in the cell cycle arrest upon infection: the CagA-dependent derepression of LATS2 by the downregulation of miR-372 and miR-373." (PMID 22027184, 2011). "LATS2 rs9552315 CT genotype may be a protective factor against infection of H. pylori." (PMID 32423384, 2020). "Compared to the control group, the infection of HCMV significantly reduced the mRNA expression of Mst1, Mst2, SAV, Lats1, Lats2, Mob1, YAP1, TAZ, TEAD1-4 genes and YAP protein expression in the Hippo-YAP pathway." (PMID 34717661, 2021). "To assess whether LATS2 upregulation was functionally relevant, we analyzed cell cycle progression of AGS cells upon infection." (PMID 22027184, 2011). "Indeed, LATS2 protein was drastically upregulated in infected AGS cells and, likewise, its mRNA level was also raised up to twofold upon infection." (PMID 22027184, 2011).
kidney diseases (1 paper, 2023).
LATS2 also shares sentences with these, for which no sentence is quoted: acute lymphoblastic leukemia (3 papers); endometrial cancer (3); soft tissue sarcoma (3); bacterial infection (2); clear cell carcinomas of the kidney (2); leukemia (2); lymph node metastasis (2); Sepsis (2); acute lung injury (1); acute myocardial infarction (1); bacterial sepsis (1); Breast (1); carcinoma in situ (1); cervical squamous cell carcinoma (1); chronic lymphocytic leukemia (1); Cyanosis (1); diabetic nephropathy (1); diffuse large B-cell lymphoma (1); ependymoma (1); fibrosarcoma (1); glioblastoma (1); head and neck squamous cell carcinoma (1); hemorrhage (1); HIV-1 infection (1); hypertrophy (1); intraepithelial neoplasia (1); invasive breast carcinoma (1); kidney chromophobe (1); lipodystrophy (1); lung carcinoids (1).
A further 23 diseases each share a sentence with LATS2 in 1 paper.